HIF1A (hypoxia inducible factor 1 subunit alpha)
Diseases named in the same sentence as HIF1A in open-access papers (continued):
Sharing a sentence is not in itself a finding about the gene and the disease.
tumor (continued). "IL-18 can also induce hypoxia-inducible factor-1α (HIF-1α), which mediates tumor progression and can encourage tumor metastasis." (PMID 39451257, 2024). "After 5 μmoL/L and 10 μmoL/L anlotinib treatment, the expression of HIF-1α in tumor cells was detected by qPCR and western blot." (PMID 38330738, 2024). "Increased levels of HIF‐1α have been associated with increased expression of VEGF, aggressive tumor growth, and poor patient prognosis." (PMID 38400671, 2024). "The positive correlation coefficient (r = 0.68) between tumor size and HIF-1α expression levels was statistically significant (P = 0.003)." (PMID 39614894, 2024). "Studies showed that the expression of the HIF-1α subunit is significantly upregulated in cancer cells and promotes tumor survival by multiple mechanisms." (PMID 38399410, 2024). "ω-alkynyl arachidonic acid and Steppogenin modulate HIF-1α to promote anti-inflammatory responses and exhibit anti-tumor effects." (PMID 39683818, 2024). "HIF-1α mediates the switch from oxidative phosphorylation to glycolysis in glucose metabolism in tumor cells, and hypoxia stimulates the Warburg effect." (PMID 38544822, 2024). "On the other hand, during tumor cell aggregation, it induced a hypoxic environment, including mitochondrial autophagy mediated by hypoxia-inducible factor 1-alpha (Hif1α) and restriction of reactive oxygen species (ROS)." (PMID 38427120, 2024). "Hypoxia-inducible factor 1-alpha (HIF-1α) is a key hypoxia responder that interacts with EZH2 to promote tumor progression." (PMID 38911968, 2024). "Of note, tumours characterized by high GLUT1 expression were also characterized by high HIF1α levels, a known transcriptional regulator of glucose transporters, including GLUT1." (PMID 38542435, 2024). "Upregulation of GLS expression promotes glutamine depletion in tumor cells, leading to HIF-1α activation and IL-23 secretion by TAMs, which can inhibit the tumor-killing effect of cytotoxic lymphocytes." (PMID 39539540, 2024). "We also identified the MAOB and MAOA genes to be under selection, where MAOB has been shown to be correlated with HiF-1α (tumour grade and hypoxia-inducible transcription factor)." (PMID 38500079, 2024). "In vivo assays showed that decreasing HCG18 expression in MDA-MB-231 cells curbed tumor growth and lung metastasis in xenograft mouse models, highlighting HIF1α’s role as a critical regulator of hypoxia-induced EMT and metastasis." (PMID 38799423, 2024). "Meanwhile, SIRT4, as a downstream target of the epigenetic regulator UHRF1, antagonizes the HIF-1α-mediated transcription of glycolytic genes, thereby inhibiting glycolysis, tumor proliferation, and metastasis." (PMID 39682281, 2024). "Altogether, our findings illustrate the complex dynamics regulating tumour progression and metastasis with emphasis on GPx2KD/HIF1α/p63 signalling driving the onset of tumour cell subpopulations undergoing phenotypic and metabolic plasticity." (PMID 38238426, 2024). "HIF-1α null and VEGF-A-null mammary tumours were associated with reduced hypoxia and decreased permeability and density of tumours." (PMID 38352889, 2024). "7-Phloroeckol is acknowledged to inhibit tumor angiogenesis in HepG2 cells and HUVECs via inhibition of HIF-1α protein expression and the secretion of VEGF protein by blocking PI3K/AKT/mTOR/P70S6K and RAS/MEK/ERK/MNK mediated signal transduction pathways." (PMID 38667760, 2024). "HIF-1α and VEGF immunophenotypes show a remarkably similar distribution around areas of tumor necrosis, which is associated with GBM tumor grade and poor prognosis." (PMID 39055895, 2024). "Most importantly, HIF-1α participates in the regulation of tumor biological behavior by reshaping the extracellular matrix in the tumor microenvironment." (PMID 38678297, 2024). "The transcription factor HIF-1α is crucial for enhancing glycolysis and promoting tumor growth in hypoxic environments." (PMID 39596452, 2024).
tumor (continued). "NE can stimulate the expression of hypoxia-inducible factor-1α (HIF-1α), which is associated with vascular endothelial growth factor (VEGF) secretion and tumor angiogenesis." (PMID 38857055, 2024). "The relationship of copper with tumor angiogenesis is significant, particularly through its interaction with HIF-1α-related pathways." (PMID 38693584, 2024). "The activation of HIF-1α facilitates rapid tumor cell adaptation to hypoxic environments, thereby contributing to the metastasis process of various malignant tumors." (PMID 38327979, 2024). "Synergy with hypoxia-inducible factor 1-alpha targeting: Inhibition of HIF-1α decreases tumor hypoxia and improves immune cell infiltration, increasing the efficacy of the combined treatments." (PMID 39493156, 2024). "The pathway regulated by HIF‐1α, which plays a role in regulating multiple signaling pathways in tumor progression and cell apoptosis and autophagy, was significantly inhibited in the PDEH group." (PMID 39118566, 2024). "Within the tumour epithelial cells, however, various NFκB related signalling pathways had corresponding upregulation such as IκKα, RelB and HIF1α." (PMID 39068768, 2024). "When HIF-1α was overexpressed, a reduction in tumor size was observed, whereas the knockdown of HIF-1α increased RCC cell proliferation." (PMID 38928435, 2024). "HIF-1α promotes the polarization of regulatory T cells and aids tumor cell proliferation, hence facilitating the development and progression of CAC." (PMID 39410090, 2024). "HIF-1α mediates the switch of glucose metabolism from oxidative phosphorylation to glycolysis in tumor cells, and hypoxia stimulates the Warburg effect." (PMID 38544822, 2024). "Currently, it is well established that HIF1α is closely related to the metabolic phenotype of tumor cells, and its expression is involved in regulating various biological activities of tumors, including drug resistance." (PMID 38195606, 2024). "HIF-1α inhibition is a promising strategy for the treatment of various tumor types, including CRC, which is based on the delay in angiogenesis and the decrease in cell viability under the conditions of hypoxia and inflammation." (PMID 39063041, 2024). "IFNα can inhibit HIF1α signaling to decrease glucose consumption by tumor cells, resulting in a higher-glucose TME." (PMID 39610917, 2024). "Strong green fluorescence emitted from responsive NBD in this probe was seen in the 4T1 tumor tissue slices obtained from a hypoxic region-containing tumor with a volume of 1,000 cm3 which was predominantly overlapped with a hypoxia marker, HIF-1α." (PMID 38994026, 2024). "In the tumor’s early stages, acute cyclic hypoxia prevails, stemming from vascular disruptions and blood supply deficits, temporarily elevating HIF-1α." (PMID 39621211, 2024). "Contrastingly, specifically deleting HIF-1α in NK cells, impaired NK-cell-mediated tumor cell-killing in vitro but inhibited tumor growth in vivo in mice." (PMID 38892084, 2024). "Simultaneously, the loaded ACF is released at the tumor site, mitigating hypoxia in tumor cells by inhibiting the expression of HIF-1α, further enhancing the treatment of CDT." (PMID 38794281, 2024). "One such angiogenic factor is HIF-1α, which maintains appropriate conditions for tumor development through metabolic adaptation to low oxygen levels and the creation of blood vessels, which favor the survival of cancer cells." (PMID 39275392, 2024). "HIF-1α is a known factor, and when therapies interfere with the same, the tumor possibilities of adapting to hypoxic situations are curbed, limiting cancer growth." (PMID 39493156, 2024). "Depletion of VBP1 was sufficient for activation of the oncogenic HIF1A pathway, which drives tumour cell migration." (PMID 38902533, 2024). "We then confirmed the target specificity of DYB‐03 in vivo and showed that tumor growth was slowed by double knockdown of HIF‐1α and EZH2 in A549, similar to the inhibitory effect of DYB‐03 on parental cells." (PMID 38072662, 2024).
tumor (continued). "Immunostaining for phosphorylated-AMPK (pAMPK) and GLUT1 (downstream of HIF1α), showed that GPx2 KD tumours were enriched in cancer cells expressing both metabolic markers." (PMID 38238426, 2024). "Glycolysis induction and PDH inhibition promote lactate accumulation, which stabilizes HIF-1α, which is a highly active metabolic pathway in tumor cells." (PMID 38399410, 2024). "Under hypoxia, the elevated expression of HIF-1α in solid tumors causes ECM remodeling, which helps in tumor progression and metastasis." (PMID 38542288, 2024). "VHL pathway activation: The level of HIF-1α can be reduced by deactivating the VHL tumor suppressor pathway." (PMID 39493156, 2024). "These interventions seek to disrupt the pathways that HIF-1α regulates, thereby impairing the tumor’s ability to adapt to hypoxia, reducing angiogenesis, and sensitizing cancer cells to conventional treatments." (PMID 39493156, 2024). "As a key transcription factor under hypoxic conditions, HIF-1α plays an important role in regulating tumor cell adaptation and angiogenesis, making it a potential therapeutic target." (PMID 39684583, 2024). "Hypoxia, a pivotal factor in the tumor microenvironment, influences the expression of numerous genes through the activation and transcription of hypoxia‐inducible factor 1‐alpha (HIF‐1α)." (PMID 39660878, 2024). "For this reason, some scholars have constructed an intelligent nanoplatform with O2 self-supply capability to reverse unfavorable hypoxic conditions, reduce the expression of HIF-1α, and promote anti-tumor effects." (PMID 39104624, 2024). "Tumor cells induce a large number of HIF-1α manifestations in response to hypoxia, which in turn activates the activation of the VEGF/VEGFR2 pathway and promotes the occurrence of angiogenesis." (PMID 39439453, 2024). "Tumor-derived lactate activates endothelial cells and stimulates angiogenesis through both HIF1A-dependent and HIF1A-independent pathways." (PMID 39529665, 2024). "Specifically, HIF-1α is involved in regulating tumor cell metabolism, apoptosis, and autophagy, thereby impacting their survival." (PMID 38799423, 2024). "Functionally, inhibition of MIF or HIF-1α in vivo significantly attenuated the tumor burden in the BM and prolonged the lifespan of AML mouse models." (PMID 37588219, 2024). "HIF-1α serves as a substrate for various kinases, including p38, and is a major regulatory mechanism in tumor tissues responding to hypoxia." (PMID 39049021, 2024). "The downregulation of HIF1A, an essential regulator of hypoxia-induced cellular response, indicates the alleviation of tumor hypoxia." (PMID 38910148, 2024). "When the HIF-1α/PD-L1 axis in malignant cells is targeted, it leads to tumor rejection and the reactivation of tumor-infiltrating lymphocytes (TILs)." (PMID 38165484, 2024). "A promising therapeutic approach for treating cancer involves focusing on HIF-1α, which influences the tumor microenvironment and boosts immune responses." (PMID 39493156, 2024). "Control of HIF-1α expression by mTOR has been previously established, astreatment with Rapa can inhibit HIF-1α in tumor cells." (PMID 38767353, 2024). "The increased expression of hypoxia-inducible factor-1α (HIF-1α) in TME facilitates the adaptation of tumor cells to hypoxia." (PMID 38880905, 2024). "ROS released from tumor cells induce oxidative stress in CAFs, leading to HIF-1α activation and enhanced glycolysis." (PMID 39438765, 2024). "This is the first study to directly associate SAA with tumor necrosis, although SAA has been previously correlated with increased HIF1α expression, which is often associated with tumor necrosis." (PMID 39336082, 2024).
tumor (continued). "Further studies have reported that HIF1A overexpression enhances ZEB1 trans-activity by binding to its promoter leading to a loss in E-cadherin causing increased invasion, migration and tumor progression." (PMID 38877052, 2024). "HIF-1α, a biomarker of tumor hypoxia, is upregulated in hypoxic conditions and is associated with tumor progression and metastasis." (PMID 38983866, 2024). "Preclinical studies have demonstrated that the inhibition of HIF-1α activity has a significant impact on tumor growth." (PMID 39582684, 2024). "In cholangiocarcinoma, SIRT3 plays a tumor-suppressive role by downregulating the HIF1α/PDK1/PDHA1 pathway, leading to tumor regression." (PMID 39620228, 2024). "In another tumor, we observed the over-expression of HIF-1A gene that has been reported in many cancers and for which diverse agents are currently being developed or are under investigation in clinical studies." (PMID 38351008, 2024). "Copper also interacts with HIF-1α, an important regulator of angiogenesis, influencing its transcriptional activity and promoting tumor growth." (PMID 38662225, 2024). "In the presence of hypoxia, tumor cells employ the Hypoxia Inducible Factor-1α (HIF-1α) to control the expression of multiple genes related to cell survival, including glycolysis, in order to generate and regulate vital elements necessary for cell survival." (PMID 38792080, 2024). "Immunohistochemical results also revealed decreased expression of Ki67, a tumor proliferation marker, and the HIF1a, GLUT1, and VEGFA proteins in OE_IDH1 H22 xenografts." (PMID 38622131, 2024). "Second, HIF-1α stabilization by PHD2/3 inactivation in activated CD8 T cells prior to their adoptive transfer increases their anti-tumor activity and appears as a promising approach to improve cancer immunotherapies." (PMID 39242595, 2024). "HIF-1α promotes TAMs differentiating from some MDSCs, inhibiting anti-tumor immunity by downregulating STAT3." (PMID 38720342, 2024). "Upon penetration into cancerous spheroids, these nanoparticles downregulate HIF-1α expression and reduce hypoxia, offering an alternative strategy to regulate cytotoxic immune cells in the tumor microenvironment and improve adoptive NK cell therapy." (PMID 39459028, 2024). "Similar to HIF-1α, HIF-2α can induce the expression of SLC38A2, SNAT2, SLC1A5 variant, GLS1, and SLC7A5, which can facilitate the rapid growth of tumor cells." (PMID 38172980, 2024). "Studies in tumour cells have shown that HIF-1α can mediate LOX expression by binding to HREs in the LOX promoter so that intensive ECM remodelling can occur to meet the demand for tumour cell invasion and metastasis." (PMID 38333108, 2024). "Studies have reported that HIF1α regulates metabolic pathways including glycolysis, while HIF2α regulates more diverse pathways such as tumor immunity and ribosomal biosynthesis." (PMID 38491188, 2024). "Further research suggested that tumour microenvironment can upregulate the protein levels of HIF-1α in B cells." (PMID 38302430, 2024). "Other reports indicate that NO suppresses the hypoxic induction of the VEGF gene by eliminating the accumulation of HIF-1α protein in VSMCs and tumor cell lines, through weakening the binding activity of HIF-1α." (PMID 38841361, 2024). "The in vivo experiments further proved that miR-21-5p carried by TAM-EVs promoted the process of tumor angiogenesis via YAP1/HIF-1α axis in HNSCC." (PMID 38602536, 2024). "In the transplanted MHCC97-H tumor tissues of nude mice, immunofluorescence experiments showed mild concordance between EphA2 and HIF-1a in terms of expression location and expression intensity (Pearson’s R value = 0.49)." (PMID 39050762, 2024). "Understanding the multifaceted roles of HIF-1α in cancer biology not only elucidates the complexities of tumor hypoxia but also opens avenues for developing novel and more effective cancer therapies." (PMID 39493156, 2024).
tumor (continued). "High levels of CXCL8 have been found to induce epithelial-mesenchymal transition and promote the proliferation, migration and invasion of tumor cells through the JAK/STAT1/HIF-1α/Snail pathway." (PMID 39488622, 2024). "Recent studies have demonstrated that SMURF2 mediates the ubiquitination and subsequent degradation of HIF1α, thereby modulating the cellular response to hypoxia—a key driver of tumor progression and metastasis." (PMID 39697237, 2024). "HIF-1α is directly involved in the regulation of the angiogenesis, metabolic reprogramming, and extracellular matrix remodeling of the tumor microenvironment." (PMID 38542288, 2024). "It has been demonstrated that HIF-1α hinders the tumor growth of RCC by suppressing cell-cycle progression regulated by c-Myc." (PMID 38666933, 2024). "Restoration of intracellular acetyl-CoA by acetate supplementation re-engages AICD, rescuing IFN-γ production in hypoxic Hif1α–/– T cells and re-sensitizing Hif1α–/– tumor-bearing mice to ICB." (PMID 39477954, 2024). "In the residual tumor lesions after treatment in the 300 and 400 J/cm2 groups, HIF-1α/PD-L1 expression was increased, indicating possible activation of tumor immune escape mechanisms." (PMID 38609977, 2024). "LOX can affect VEGF induction, HIF-1α activation, and other mechanisms, playing an important role in the occurrence, development, invasion, and metastasis of various tumor." (PMID 39132501, 2024). "Co-delivery of chemotherapy drugs and other drugs suppressing HIF1α expression promotes anti-tumor therapy." (PMID 38831883, 2024). "The involvement of HIF-1α in facilitating the rapid adaptation of tumor cells to the anoxic microenvironment and thus plays crucial roles in OS metastasis." (PMID 38327979, 2024). "HIF1α promotes the utilization of glucose and oxygen by tumor cells, and increases the activity of oxidative phosphorylation and tricarboxylic acid cycling." (PMID 38195606, 2024). "Several studies have shown that blocking the activation of HIF-1α can significantly inhibit tumor angiogenesis and progression." (PMID 39308869, 2024). "In the tumor edge regions of control animals, the hypoxia marker HIF1α was detected in the nucleus and cytoplasm." (PMID 38378689, 2024). "For instance, the stiffening of the ECM enhances the Warburg effect through ROS/HIF-1α signaling, thereby driving tumor growth." (PMID 39684583, 2024). "In this study, molecular analysis was carried out for the HIF-1α in malignant cells within the tumor." (PMID 38313904, 2024). "The activation of hypoxia-inducible factor 1α (HIF1α) is a critical factor in regulating glycolysis in tumor cells." (PMID 39769177, 2024). "HIF-1α not only drives tumor cells to adapt to hypoxic conditions and proliferate but also serves as a central regulator of tumor-immune escape." (PMID 39698411, 2024). "In another study, under hypoxic conditions, HIF-1α was shown to induce upregulation of the tumor cell MALAT1, further promoting the growth and spread of triple-negative breast cancer (TNBC) cells by autophagy activation." (PMID 39421736, 2024). "The increased miR-21-5p subsequently degrades its downstream HIF-1αN (a HIF-1α subunit inhibitor) by targeting its 3′-UTR, leading to the activation of the tumor-promoting HIF-1α/VEGF pathway." (PMID 38602536, 2024). "Significantly, oxythiamine is capable of inhibiting HIF-1α-induced glycolysis, which in turn enhances the sensitivity of tumor cells to drugs." (PMID 37588219, 2024). "HIF1A gene expression is upregulated in the tumour compartment of both p16+/HPV- and p16-/HPV- OPC relative to p16+/HPV+, and also in the stromal compartment of p16-/HPV-." (PMID 39328208, 2024). "The balance between BMAL1 and HIF1α affects macrophage metabolism and anti-tumor immunity, and BMAL1 knockout increases septic mice mortality." (PMID 38678017, 2024). "In 2021, Deng et al73 showed that HIF-1α can result in tumor immune escape by mediating the up-regulation of PD-L1, which in turn leads to disease progression." (PMID 37588219, 2024).